ADA (adenosine deaminase)
Diseases named in the same sentence as ADA in open-access papers (continued):
Sharing a sentence is not in itself a finding about the gene and the disease.
Immunodeficiency (continued). "The same correlation was not documented in ADA-SCID and WAS diseases, where immunodeficiency is often associated with growth impairment and age increase does not always correspond to weight increase." (PMID 31150018, 2019). "However, other immunodeficiencies also display bone abnormalities, and bony pathology that is supposedly characteristic to ADA-SCID has been found in patients with normal ADA activity, albeit to a lesser extent." (PMID 27579027, 2016).
tuberculous pleurisy (66 papers, 2008 to 2026). "Malignant pleural effusion caused by lymphoma can be easily misdiagnosed as tuberculous pleurisy, as both conditions commonly show markedly elevated levels of ADA and LDH." (PMID 41480553, 2025). "Increased pleural fluid adenosine deaminase (ADA) is useful for diagnosing tuberculous pleurisy (TB), but high ADA levels are associated with other diseases." (PMID 36131272, 2022). "These factors can help diagnose patients with high ADA levels; thus, we developed a diagnostic flowchart for tuberculous pleurisy by using predicted factors with high diagnostic accuracy." (PMID 36131272, 2022). "This is often difficult, thus other diagnostic tests have been proposed for the diagnosis of pleural tuberculosis, such as adenosine deaminase (ADA) assay." (PMID 30428535, 2018). "ADA as a diagnostic marker is routinely used for the diagnosis of tuberculous pleuritis with a high degree of specificity and sensitivity." (PMID 29043661, 2018). "Adenosine deaminase (ADA) is currently used as a diagnostic marker for tuberculous pleuritis." (PMID 29043661, 2018). "Therefore, we underline another utility of ADA besides its known role in tuberculous pleurisy." (PMID 34575641, 2021). "Pleural fluid analysis demonstrated an exudative effusion with markedly elevated adenosine deaminase (ADA) levels (130 U/L), consistent with tuberculous pleuritis." (PMID 41859595, 2026). "Laboratory tests showed a lymphocytic exudative effusion with elevated adenosine deaminase, initially suggesting tuberculous pleuritis." (PMID 41767082, 2026). "The significance of ADA and LDH as diagnostic biomarkers for pleural tuberculosis is well established." (PMID 38336640, 2024). "Due to the shortcomings associated with the microbiological tests, pleural fluid adenosine deaminase (ADA) has been commonly used as a surrogate biomarker to establish the diagnosis of pleural tuberculosis." (PMID 39715545, 2024). "A systematic review and meta-analysis showed that the combined test of sTREM-1 and ADA had a sensitivity of 90.4% and a specificity of 82.4% for diagnosing tuberculous pleurisy." (PMID 38089819, 2023). "Approximately 50% of extrapulmonary TB patients are diagnosed with tuberculous pleurisy, which is characterized by a severe immune response with high exudation of adenosine deaminase (ADA), lymphocyte enrichment, and local exudation of neutrophils." (PMID 38089819, 2023). "In particular, the possibility of tuberculous pleurisy due to elevated levels of adenosine deaminase was considered, further complicating the diagnosis." (PMID 37965415, 2023). "Previous reports demonstrated that 3.0–49.0% of patients with ADA levels of ≥ 40 U/L had diseases other than tuberculous pleurisy." (PMID 36131272, 2022). "The odds ratios of pleural fluid LDH < 825 IU/L and LDH/ADA < 26 for diagnosis of tuberculous pleurisy were 12.90 (95% confidence level [Cl] 6.47–25.5) and 4.44 (95%Cl 2.12–9.31), respectively." (PMID 36131272, 2022). "The most frequent disease with ADA levels of ≥ 40 U/L was tuberculous pleurisy; however, approximately 60% of patients were diagnosed with other diseases." (PMID 36131272, 2022). "Adenosine deaminase (ADA) is an enzyme produced by lymphocytes, and an elevated level of ADA in pleural fluid is a useful marker for the diagnosis of tuberculous pleurisy." (PMID 36131272, 2022). "The higher the ADA levels are, the higher the likelihood of tuberculous pleurisy is, and an ADA level above 70 U/L is more reliable for diagnosing tuberculous pleurisy." (PMID 36131272, 2022). "This study shows that only 40.0% of patients with ADA levels of ≥ 40 U/L are diagnosed with tuberculous pleurisy and that several biomarkers are helpful for diagnosis." (PMID 36131272, 2022). "The diagnostic flowchart based on those predicted factors is a helpful supplement for distinguishing tuberculous pleurisy from other diseases with high ADA levels." (PMID 36131272, 2022).
tuberculous pleurisy (continued). "A case involving high pleural fluid ADA levels should be investigated using several factors to distinguish tuberculous pleurisy from other diseases." (PMID 36131272, 2022). "The rate of patients with tuberculous pleurisy was 40.0% (n = 203), and 60.0% of patients among those with ADA levels of ≥ 40 U/L were diagnosed with other diseases." (PMID 36131272, 2022). "ADA testing is currently recognized as an ideal indicator for the diagnosis of tuberculous pleurisy." (PMID 34425761, 2021). "The ADA assay has a high sensitivity (80%) and specificity (94%) and hence it is still a useful tool for the diagnosis of pleural tuberculosis." (PMID 31534914, 2019). "The current study showed high ADA sensitivity (80%) and specificity (94%) for the diagnosis of pleural tuberculosis." (PMID 31534914, 2019). "The aim of this study was to evaluate the usefulness of an adenosine deaminase assay and real-time polymerase chain reaction (qPCR) in diagnosing pleural tuberculosis." (PMID 31534914, 2019). "The ADA levels among the confirmed pleural tuberculosis cases ranged from 8 units/L to 134.3 units/L with a mean ADA value of 52.2 ± 21.66 units/L." (PMID 31534914, 2019). "Operating characteristics of real-time polymerase chain reaction and adenosine deaminase assay in comparison with the gold standard culture in pleural tuberculosis, Pretoria, South Africa, 2008-2009." (PMID 31534914, 2019). "In this study, the sensitivity and specificity of the ADA assay to diagnose pleural tuberculosis in HIV infected patients were lower than that reported in non-HIV infected patients." (PMID 30428535, 2018). "Tuberculous pleuritis usually presents as an acute illness with fever, cough and pleuritic chest pain, and is diagnosed by elevated levels of adenosine deaminase (ADA) and interferon-gamma (IFNγ) in the pleural fluid." (PMID 29101376, 2017). "An adenosine deaminase (ADA) level above 70 U/ml is regarded as adequate for diagnosing pleural tuberculosis and has eliminated the need for invasive techniques such as pleural biopsy." (PMID 25243068, 2014). "Further improvements in the limit of detection of an ICT for IFNg, and possibly combination of IFNg with other biomarkers such as adenosine deaminase, are necessary for such a test to be of value in the evaluation of pleural tuberculosis." (PMID 24376880, 2013). "Specifically, a meta-analysis of 63 studies of ADA in tuberculous pleuritis reveals that the sensitivity of the test is of 0.92 (95% CI 0.90–0.93) and specificity of 0.90 (95% CI 0.89–0.91)." (PMID 22529869, 2012). "On the other hand, ADA levels in pleural fluid are also elevated in renal transplant recipients with tuberculous pleurisy." (PMID 22723878, 2012). "Most of the ADA in pleural tuberculosis is ADA2; although better than total ADA for diagnosing pleural tuberculosis, the separation of ADA into its isoenzymes is more expensive than the basic ADA test, not readily available and its use is so far limited." (PMID 22723878, 2012). "ADA-2 isoform is the one raised in tuberculous pleurisy, accounting for almost 88% of total ADA activity." (PMID 21811524, 2010). "Adenosine deaminase estimation in pleural fluid has long been taken as a marker for tuberculous pleurisy." (PMID 21811524, 2010). "These three parameters however were strikingly changed at the second visit 4-months later, when the TST was positive, the pleural fluid was predominantly lymphocytic, the ADA level was elevated and tuberculous pleurisy was diagnosed." (PMID 19175931, 2009). "Correlation (r) values for ADA and other blood and pleural fluid markers in tuberculous pleuritis patients (N = 197)." (PMID 18665218, 2008). "A well established biological marker for diagnosis of tuberculous pleuritis is Adenosine Deaminase Activity (ADA)." (PMID 18665218, 2008). "ADA analysis is a sensitive marker of tuberculous pleuritis even in HIV patients with very low CD4 counts in a high TB endemic region." (PMID 18665218, 2008).
tuberculous pleurisy (continued). "The ADA assay is inexpensive, rapid, and simple to perform and is of great value for the immediate diagnosis of tuberculous pleuritis while waiting for culture result and this has a positive impact on patient outcome." (PMID 18665218, 2008). "Adenosine deaminase (ADA) is a useful biomarker for the diagnosis of tuberculous pleurisy (TBP)." (PMID 38178065, 2024). "The level of ADA was low, and it was difficult to diagnose Tuberculous pleuritis." (PMID 36747130, 2023). "However, in our study, diseases other than tuberculous pleurisy were present in 21.8% of patients with ADA levels of ≥ 70 IU/L." (PMID 36131272, 2022). "The level of adenosine deaminase in pleural fluid together with cell count, other routine biochemical parameters and age, combined with a machine-learning approach, is suitable for the diagnosis of pleural tuberculosis in a low prevalence scenario." (PMID 34735491, 2021). "Combined IL-33, ADA, TSPOT.TB, the diagnostic specificity was 100%, and the sensitivity was 88.5%, suggesting that the combined detection has a higher diagnostic value for tuberculous pleurisy." (PMID 34425761, 2021). "Adenosine deaminase (ADA) is a biomarker of pleural tuberculosis." (PMID 29854023, 2018). "In conclusion, ADA level determination could be useful to diagnose pleural tuberculosis in HIV infected patients, although larger multicentric studies are necessary to confirm this." (PMID 30428535, 2018). "Besides that, the results found in the present study are in agreement with previous reports which show IFN-γ as a better marker than ADA for the diagnosis of tuberculous pleurisy, and bringing IP-10 as an alternative method, although its poor performance." (PMID 30148839, 2018). "Recently it was reported that the increased ADA activity was not restricted in tuberculous pleurisy but in the pleural fluid associated with pyothorax, lymphoma or ILS." (PMID 24984978, 2014). "One of the major concerns regarding the sensitivity of ADA was its reliability in immunocompromised patients; however, more recent studies have demonstrated that ADA is a reliable marker of tuberculous pleurisy in HIV-positive patients, even in those with a low CD4 T-cell count." (PMID 22723878, 2012). "The overall sensitivity of the ADA assay in diagnosing tuberculous pleuritis was 94%." (PMID 18665218, 2008). "Therefore, measuring hyaluronic acid in combination with adenosine deaminase in pleural fluid could lead to a more effective diagnosis for tuberculous pleurisy." (PMID 25368701, 2015). "However, it was reported that ADA activity may be lower at the early stage of tuberculous pleurisy and the high activities may decrease long after onset of the disease as well." (PMID 24984978, 2014). "It often shows an increase in lymphocytes with elevated adenosine deaminase (ADA), which is usually confused with tuberculous pleurisy." (PMID 41480553, 2025). "Summary of findings from studies evaluating pleural fluid adenosine deaminase (ADA) and unstimulated pleural fluid interferon-gamma (IFN-γ) for diagnosing pleural tuberculosis." (PMID 34166463, 2021). "Definition of abbreviations: TBP, tuberculous pleuritis; CHF, congestive heart failure; LDH, lactate dehydrogenase; ADA, adenosine deaminase; RPT, residual pleural thickening." (PMID 26367274, 2015). "Previous reports showed some predictive factors for distinguishing between tuberculous pleurisy and other diseases regardless of ADA levels." (PMID 36131272, 2022). "This indicates that compared to patients without TPE, patients with tuberculous pleurisy have a 58-fold higher chance of being ADA.IL-27 assay positive." (PMID 33436672, 2021). "In our study, ADA levels were above the cut-off of 30 units/L value in two (5.8%) patients for whom the diagnosis of pleural tuberculosis was ruled out; both the patients had pneumonia with ADA levels of 98 units/L and 39.8 units/L." (PMID 31534914, 2019).
tuberculous pleurisy (continued). "Other predictive rules have been published for differentiating tuberculous pleurisy from malignant effusion; however, these include the determination of ADA or other tests which are not widely available." (PMID 30813590, 2019). "The accumulation of ADA in pleural fluid results mainly from one of its isoforms, ADA2, with which a diagnosis of tuberculous pleurisy could be verified." (PMID 24984978, 2014). "Interferon gamma is considered to be a better marker than ADA for the diagnosis of tuberculous pleuritis, since its estimation is not affected by immununosuppression." (PMID 18665218, 2008). "The aim of this study was to evaluate the sensitivity of ADA in tuberculous pleuritis patients with low CD4 counts and to determine whether there was any correlation between CD4 cell counts and ADA values." (PMID 18665218, 2008). "Although this background increases the complexity of the diagnosis, thoracic CT scanning does not see recurrent lesions, sputum smears and culture do not see mycobacteria, and adenosine deaminase is normal, making the basis for the diagnosis of tuberculous pleurisy weak." (PMID 39705491, 2024). "A higher or lower ADA level is correlated with a worse survival when compared to a normal level, indicating that the level of ADA may not have an obvious diagnostic performance in the differential diagnosis of TPE and MPE, although it passes a great diagnostic efficiency of pleural tuberculosis." (PMID 34163438, 2021). "However, elevated ADA may not be limited to tuberculous pleuritis, as it is also present in LC or MPM." (PMID 26689234, 2015).
combined immunodeficiency (41 papers, 2009 to 2025). A broad classification of inherited disorders presenting at birth that affect both the cell-mediated and humoral aspects of the immune response. "Here, the authors show a case of T-cell acute lymphoid leukaemia in a patient with Adenosine Deaminase-deficient Severe Combined Immunodeficiency (ADA-SCID) treated with retroviral gene therapy." (PMID 38688902, 2024). "Few reports highlighted BM defects in severe combined immunodeficiencies (SCID), such as adenosine deaminase-SCID (ADA-SCID) with myeloid dysplasia, marrow hypocellularity, and a reduced frequency of HSCs." (PMID 35631417, 2022).
lymphoma (40 papers, 2011 to 2026). A malignant (clonal) proliferation of B- lymphocytes or T- lymphocytes which involves the lymph nodes, bone marrow and/or extranodal sites. "Specifically, among effusions linked to lymphoma, elevated ADA levels are more frequently associated with T‐cell neoplasms than with B‐cell neoplasms." (PMID 39563685, 2024). "Elevated levels of adenosine deaminase, fms-related tyrosine kinase 3 ligand, and fractalkine have been associated with autoimmune diseases, lymphoma, and atherosclerosis in animal and observational studies." (PMID 39351220, 2024). "Eight cases of lymphoma have been reported to date in ADA-SCID patients, and half of them are EBV associated." (PMID 29456531, 2018). "It would be also interesting to investigate whether lymphoma cells spontaneously reverted the ADA mutation, as observed in selected cases of ADA-SCID patients." (PMID 29456531, 2018). "Previously, it was reported that increased CSF ADA level can be caused by other diseases such as sarcoid meningitis, meningeal involvement with leukemia or lymphoma, cerebral toxoplasmosis, cerebral infarction, neurosyphilis, listeria meningitis, and other aseptic meningitis." (PMID 28028491, 2016). "Adenosine deaminase (ADA) is widely used in TB-endemic regions due to its low cost and high diagnostic accuracy, although its specificity may be reduced in certain conditions, such as empyema, lymphoma, and rheumatoid pleuritis." (PMID 42226837, 2026). "A significant increase in adenosine deaminase levels has been demonstrated in various tumor tissues, including cholangiocarcinoma, lymphoma, diffuse large B-cell lymphoma, and pancreatic adenocarcinoma." (PMID 39546272, 2025). "It's important to note that elevated pleural fluid ADA levels can also occur in conditions other than TB, such as bacterial empyema, mesothelioma, lung cancer, lymphoma, parapneumonic effusion, and hematologic malignancies." (PMID 39416574, 2024). "Immuno-deficient patients are known to be prone to hematological malignancies and 10 cases of lymphoma have been described in ADA-SCID patients undergoing ERT45,46." (PMID 38688902, 2024). "Next, deoxycoformycin is an inhibitor of adenosine deaminase and a common anticancer chemotherapeutic drug for leukemia and lymphoma treatment." (PMID 37122566, 2023). "Together, these findings lay the groundwork for pursuing ADA and purine metabolism pathways as targets for more selective therapies to treat EBV-associated lymphoid cancers." (PMID 33497421, 2021). "Clinical, genetics, and biological characteristics of ADA-SCID patients who developed lymphoma (review of the published cases)." (PMID 29456531, 2018). "Since lymphoma related malignant pleural effusion can also have high ADA level and can mimic TPE, further study including larger number of patients with MPE from lymphoma is needed." (PMID 28070157, 2016). "A variety of pleural conditions lead to an elevated PF ADA level, with pleural malignancies (especially lymphomas), rheumatoid pleurisy and parapneumonic effusion being the leading causes." (PMID 24386296, 2013). "ADA measurement has a limited value in regions of low TB prevalence as it can also be elevated in patients with empyema, lymphoma, lung cancer, rheumatoid arthritis, systemic lupus erythematosus, brucellosis, and Q fever." (PMID 22474483, 2012). "NP expression has also been used to determine the clinical severity of various types of leukemias and lymphomas especially as a ratio to adenosine deaminase (ADA)." (PMID 21448452, 2011). "Nevertheless, we have to underline that lymphomas were not included in the malignant group, as numerous studies have demonstrated high p-ADA levels among lymphoma pleural effusions as a response to lymphocytes proliferation." (PMID 34575641, 2021). "Nine cases of lymphoma have been described in ADA-SCID patients, including the present case." (PMID 29456531, 2018).